CDHR2 (cadherin related family member 2)
Description:
Intermicrovillar adhesion molecule that forms, via its extracellular domain, calcium-dependent heterophilic complexes with CDHR5 on adjacent microvilli. Thereby, controls the packing of microvilli at the apical membrane of epithelial cells. Through its cytoplasmic domain, interacts with microvillus cytoplasmic proteins to form the intermicrovillar adhesion complex/IMAC. This complex plays a central role in microvilli and epithelial brush border differentiation. May also play a role in cell-cell adhesion and contact inhibition in epithelial cells.
Synonyms: PC-LKC; PCDH24; PCLKC; FLJ20124; FLJ20383; PCLCK
Tractability: Antibody: UniProt places it where antibodies can reach, with high confidence; its Gene Ontology location is reachable by antibodies, with high confidence; UniProt predicts a signal peptide or a membrane-spanning region. PROTAC: its protein half-life has been measured.
Gene: Protein-coding gene on chromosome 5 (176,542,511 to 176,596,284, forward strand). Ensembl gene ENSG00000074276.
Subcellular location: Apical cell membrane; Cell projection, microvillus membrane; Cell junction
Gene Ontology:
Molecular function: cell adhesion molecule binding; protein binding; calcium ion binding
Biological process: brush border assembly; cell-cell adhesion mediated by cadherin; epithelial cell differentiation; intermicrovillar adhesion; negative regulation of cell growth involved in contact inhibition; regulation of microvillus length; axonogenesis; cell adhesion; cell differentiation; cell-cell adhesion; epithelium development; homophilic cell-cell adhesion
Cellular component: anchoring junction; apical plasma membrane; brush border; brush border membrane; extracellular exosome; microvillus; microvillus membrane; plasma membrane; adherens junction; membrane
Genetic constraint (gnomAD): Loss-of-function variants: 105 observed, 140.29 expected, observed/expected ratio (o/e) 0.75, 90% interval 0.64 to 0.88. The upper end of that interval is the gene's LOEUF score, 0.88, which puts it in group 3 of 6, group 1 being the genes least tolerant of losing a copy. Missense variants: 1,624 observed, 1,788 expected, observed/expected ratio (o/e) 0.91, 90% interval 0.87 to 0.95. Synonymous variants: 755 observed, 765.08 expected, observed/expected ratio (o/e) 0.99, 90% interval 0.93 to 1.05.
Homologues: Orthologues: chimpanzee CDHR2 (99% identical), macaque CDHR2 (90% identical), dog CDHR2 (78% identical), rabbit CDHR2 (75% identical), pig CDHR2 (73% identical), mouse Cdhr2 (73% identical), rat Cdhr2 (72% identical), guinea pig CDHR2 (70% identical). Paralogues in human: CDH23 (21% identical), DCHS2 (20% identical), DCHS1 (20% identical), CDHR1 (18% identical), PCDH7 (17% identical), PCDH9 (17% identical), PCDH1 (16% identical), PCDH11X (16% identical), PCDH11Y (16% identical), PCDH20 (15% identical), CDH4 (15% identical), CDH1 (14% identical), and 21 more.
Diseases named in the same sentence as CDHR2 in open-access papers:
CDHR2 is named in the same sentence as 11 diseases in open-access papers, as found by Europe PMC text mining. Sharing a sentence is not in itself a finding about the gene and the disease. The quoted sentences say what the papers report.
inflammatory bowel disease (2 papers, 2022 to 2025). A spectrum of small and large bowel inflammatory diseases of unknown etiology. "Deletion of IMAC components such as cadherin-related family member-2 (CDHR2) in mice resulted in microvillus disorganization and fanning, a structural aberration that is also found in the brush border of patients with inflammatory bowel disease." (PMID 39092422, 2022).
colitis (1 paper, 2023). Inflammation of the colon. "We have not observed spontaneous colitis in CDHR5‐deficient mice nor has it been reported in CDHR2‐ and TMIGD1‐deficient mice." (PMID 37691494, 2023).
COVID-19 (1 paper, 2023). A disease caused by infection with severe acute respiratory syndrome coronavirus 2. "Four of the five intestine-enriched proteins, i.e., ZG16, NLRP6, APOA4, and VIL1, showed decreased levels in serum of COVID-19 patients, whereas only CDHR2, a microvillar protein, showed elevated levels." (PMID 37739942, 2023).
schizophrenia (1 paper, 2022). A major psychotic disorder characterized by abnormalities in the perception or expression of reality. "Our expression analysis revealed increased H3K9me2 and decreased expression of CDHR2; decreased H3K9me2, and increased expression of CDH20, suggesting that symptoms typically reported by individuals with schizophrenia may be caused by dysregulation spread throughout the cadherin system." (PMID 36386965, 2022).
tumor (10 papers, 2011 to 2025). "The expression levels of Cdhr2 and Cdx2, which act as tumor suppressors, were more pronouncedly downregulated in tumors from Ifngr1−/−ApcMin/+ mice." (PMID 27286456, 2016). "Additional, novel aberrations included case 11 that had a 3.6-Mb gain that encompassed 5q35.2q35.3 and included CDHR2, a tumor suppressor candidate." (PMID 22087757, 2011). "Additionally, knocking down Ndrg1 in BLM tumor organoids reduced secretory progenitor marker gene expression (Sox4, Atoh1, Dll1, Notch1), but increased enterocyte marker gene expression (Cdhr2, Aqp8)." (PMID 38893159, 2024). "Also, we identified novel predicted tumor-suppressive ligands (SLIT3, DCN, CCN3, THBS1, INHA and INHBA), proteins (DNASE1L3, SULF1, PTEN, OAS1, and DAB2IP), and receptors (P2RX4, CDHR2, PTPRJ, and PTPRH) in MSC1 cells." (PMID 40564222, 2025).
cancer (6 papers, 2019 to 2025). A tumor composed of atypical neoplastic, often pleomorphic cells that invade other tissues. "For example, CDHR2 is involved in the surface structure of epithelial cells, which are present in various human organs and related to cancer aetiology." (PMID 41071435, 2025). "LAMP1 and LAMP2 were expressed in the cytoplasm of cancer cells and inflammatory cells, whereas CDHR2 was only expressed in the cytoplasm of cancer cells." (PMID 31425520, 2019).
psychiatric disorder (1 paper, 2022). A disorder characterized by behavioral and/or psychological abnormalities, often accompanied by physical symptoms. "Cadherin family members CDHR2 and CDH20 are intercellular adhesion molecules associated with psychiatric disorders." (PMID 36386965, 2022).
CDHR2 also shares sentences with these, for which no sentence is quoted: colorectal cancer (2 papers); liver cancer (2); fatty liver (1); infection (1).